SHBG (sex hormone binding globulin)
Diseases named in the same sentence as SHBG in open-access papers (continued):
Sharing a sentence is not in itself a finding about the gene and the disease.
Insulin resistance (continued). "Taken together these and other data suggest that circulating levels of SHBG are a marker of the presence and severity of hepatic insulin resistance, de novo lipogenesis, and associated conditions including NAFLD, type 2 diabetes, and cardiovascular disease." (PMID 29995902, 2018). "Hyperinsulinemia and insulin resistance are associated with low SHBG levels, suggesting that insulin level and/or insulin resistance is suppressive to SHBG production." (PMID 30057912, 2018). "Sex hormone-binding globulin (SHBG), a glycoprotein synthesized by hepatocytes, has been linked to insulin resistance and hepatic lipid metabolism and is suggested to be associated with nonalcoholic fatty liver disease (NAFLD)." (PMID 30455723, 2018). "In contrast, increasing free T or decreasing SHBG concentrations were associated with a higher BMI, as well as higher insulin levels and insulin resistance, but this association disappeared after adjusting for BMI." (PMID 30275830, 2018). "In men, low serum SHBG levels are associated with insulin resistance, obesity, non-alcoholic fatty liver disease (NAFLD), type 2 diabetes (T2D), and cardiovascular disease." (PMID 29995902, 2018). "Causes of decreased SHBG concentrations include obesity, insulin resistance and type 2 diabetes mellitus, exogenous androgen, anabolic steroid or glucocorticoid use and nephrotic syndrome." (PMID 28344518, 2017). "Lower SHBG, associated with insulin resistance and GDM, was noted in obese GDM women at both time points, adding to the evidence that low SHBG reflects insulin resistance rather than obesity per se." (PMID 28766127, 2017). "Circulating Sex hormone binding globulin (SHBG) levels are inversely associated with insulin resistance." (PMID 28279160, 2017). "Low SHBG has been linked with an elevated HOMA-IR (consistent with increased insulin resistance), in both men and women." (PMID 28458728, 2017). "The current study shows that serum SHBG is significantly associated with metabolic disorders of abdominal obesity, liver enzyme, blood lipids, and insulin resistance." (PMID 29109457, 2017). "Low circulating SHBG levels are also associated with insulin resistance, itself a characteristic feature of T2DM with insulin resistance playing a major role in its pathogenesis." (PMID 28458728, 2017). "SHBG level is known to be inversely correlated with insulin resistance and is a predictor of the risk of type 2 diabetes." (PMID 27725831, 2016). "Traditionally, BMI was thought to be the independent predictor of circulating SHBG level and hyperinsulinemia, which was caused by insulin resistance and resulted in the impairment of SHBG synthesis in the liver." (PMID 27583401, 2016). "The decrease of SHBG level was also a risk factor for insulin resistance in both PCOS and metabolic disturbance." (PMID 25223276, 2014). "It is believed that increased insulin resistance associated with increased central obesity leads to decreased sex-hormone binding globulin, leading to increased free testosterone and estradiol promoting bone formation." (PMID 25229052, 2014). "In premenopausal women with polycystic ovary syndrome, it has been reported that testosterone and SHBG were associated with insulin resistance." (PMID 23825975, 2013). "We found that the associations of estradiol, testosterone and SHBG with insulin resistance were different in premenopausal women, postmenopausal women and postmenopausal women who had received hormone therapy." (PMID 23825975, 2013). "Post-menopausal women with hypertension had significantly lower SHBG concentrations, and this association was significant even after adjusting for major risk factors for hypertension such as age, BMI, diabetes and insulin resistance." (PMID 23594436, 2013). "Taken together, these findings indicate that a significant inverse association exists between circulating SHBG and insulin resistance." (PMID 29043159, 2013).
Insulin resistance (continued). "Testosterone and sex hormone-binding globulin (SHBG) as well as estrogen are also associated with insulin resistance in women." (PMID 23825975, 2013). "Interest has recently been shown in biological functions of SHBG associated with insulin resistance beyond its role as simply a transporter of sex steroid hormones." (PMID 23825975, 2013). "In our study a weak association between insulin resistance and hypertension was observed in men were SHBG had stronger association with hypertension than HOMA-Ir." (PMID 23594436, 2013). "We investigated the association between SHBG and insulin resistance in type 2 diabetic diabetic men in a hospital in Nigeria." (PMID 29043159, 2013). "A significant inverse association between insulin resistance and SHBG was observed (r = 0.353, p < 0.015)." (PMID 29043159, 2013). "A weak (though statistically significant) inverse association (r = 0.353, p < 0.015) was observed between insulin resistance and SHBG, whereas a positive association (r = 0.356, p < 0.014) was observed between age and circulating SHBG." (PMID 29043159, 2013). "While this study was limited to male participants, a low SHBG has also been shown to be associated with obesity, insulin resistance, and the metabolic syndrome in women." (PMID 22844441, 2012). "It has been noted that Asian women have greater amounts of visceral fat – the adipose tissue component most strongly associated with insulin resistance and lower sex hormone-binding globulin – for a given waist measurement than Caucasian women." (PMID 19223908, 2009). "Similarly to insulin resistance, vitamin D deficiency is associated with decreased levels of SHBG, leading to elevated free testosterone." (PMID 40149685, 2025). "Therefore, the purpose of this study is to investigate the relationships between insulin resistance, vitamin D deficiency, BMI, and hyperandrogenism (assessed using both serum testosterone and SHBG levels) in PCOS patients." (PMID 40868057, 2025). "Insulin resistance is also associated with an increase in hepatic fat and numerous studies have reported a strong inverse relationship between liver fat accumulation and circulating SHBG levels." (PMID 40863113, 2025). "Additionally, obesity is often associated with insulin resistance, leading to lowered levels of SHBG and reduced free T, further impairing Sertoli cell function." (PMID 40463744, 2025). "In our study, we did not observe a significant contribution of insulin resistance (i.e., HOMA-IR) to testosterone rises over time, but BMI increments and SHBG reductions, which are consistent with a condition of insulin resistance, were associated with testosterone rises." (PMID 41155322, 2025). "Importantly, reduced SHBG levels have been linked to insulin resistance and a heightened risk of developing type 2 diabetes mellitus, irrespective of other sex hormones, in both sexes." (PMID 40495241, 2025). "Insulin resistance and hyperinsulinemia can reduce SHBG, leading to increased risk of OSA." (PMID 39996383, 2025). "Nevertheless, it might support a possible role in the regulation of insulin resistance by SHBG independently from weight loss, as recently suggested by several studies in men33, 34, 35 and women." (PMID 40105090, 2025). "On the other hand, insulin resistance status is associated with low expression of SHBG." (PMID 38988998, 2024). "Our results regarding preeclampsia, however, may be confounded by the fact that the preeclampsia group had a significantly higher BMI, which is a well-known risk factor for preeclampsia as well as insulin resistance, and the latter may influence SHBG levels." (PMID 39410647, 2024). "Studies have found several polymorphisms in the SHBG gene to be associated with insulin resistance and T2D, showing that altered SHBG physiology may trigger the pathogenesis of T2D." (PMID 38954350, 2024). "However, sex hormone-binding globulin (SHBG) was inversely associated with insulin resistance and type 2 diabetes in both men and women." (PMID 38884020, 2024).
Insulin resistance (continued). "Furthermore, obesity has been associated with insulin resistance and hyperinsulinemia, which downregulates sex hormone binding globulin production, and, thus, results in increased levels of circulating estradiol." (PMID 39061008, 2024). "In this context, SHBG seems to be independently associated with insulin resistance in our study." (PMID 39014506, 2024). "Low postmenopausal SHBG concentrations are associated with central obesity and insulin resistance." (PMID 38650726, 2024). "According to the most recent research, low human sex hormone-binding globulin (SHBG) serum levels correlate with an increased risk of obesity, insulin resistance and diabetes, and may contribute to overall metabolic dysregulations." (PMID 37697311, 2023). "SHBG is thus gaining more attention as it might be a potential therapeutic factor in the treatment of obesity and associated inflammation and insulin resistance." (PMID 38146533, 2023). "In contrast to lipodystrophies, severe insulin resistance due to insulin receptoropathy is associated with the absence of non-alcoholic steatohepatitis, a normal lipid profile, normal or high levels of adiponectin and sex hormone-binding globulin (SHBG)." (PMID 36331627, 2023). "Thus, insulin resistance in obesity is associated with suppressed serum sex hormone-binding globulin (SHBG), which contributes to elevated serum levels of circulating free 17-β-oestradiol (E2) and testosterone." (PMID 37233716, 2023). "Moreover, insulin resistance is also associated with this disorder, where excess androgen leads to the reduced sex hormone-binding globulin (SHBG) by inhibiting its synthesis of in the liver." (PMID 36556340, 2022). "SHBG is inversely associated with insulin resistance and development of GDM, however, the mechanism for this association remains unclear." (PMID 36295825, 2022). "This effectively reduces the potential direct biological effects of SHBG and its confusion with obesity and insulin resistance, although cluster-filtered testosterone variants may still have secondary effects in SHBG levels." (PMID 35615721, 2022). "The main limitation of the present study is the lack of euglycemic-hyperinsulinemic clamp and assessment of fatty liver, as well as recognized diagnostic tests for NAFLD because NAFLD is a cause of liver insulin resistance development and decreased SHBG synthesis." (PMID 35140785, 2022). "Similarly, insulin resistance induced by adiposity is linked to a decreased level of sex-hormone-binding globulin, which increases sex steroid bioavailability and precipitates early breast development." (PMID 36062089, 2022). "However, the causal relationships between low SHBG levels and T2D risk have been reported similarly in both sexes, though an effect on insulin resistance." (PMID 36505380, 2022). "Based on further MR reports, genetically-predicted higher SHBG may lower insulin resistance and T2D risk in men and women." (PMID 36601008, 2022). "Obesity may impact the risk of PCOS via insulin resistance and compensatory hyperinsulinemia, which augments ovarian/adrenal androgen production and suppresses sex hormone–binding globulin (SHBG), thereby increasing androgen bioavailability." (PMID 35488014, 2022). "Circulating SHBG levels are influenced by metabolic and hormonal factors, and they are reduced in obesity and insulin resistance, suggesting that SHBG may have a broader clinical utility in assessing the risk for cardiovascular diseases." (PMID 34335746, 2021). "A cross-sectional study in 156 age-matched women with or without PCOS showed that diacylglycerol and triacylglycerol were inversely associated with SHBG, positively associated with homeostasis assessment of insulin resistance, free androgen index, and waist circumference." (PMID 34416878, 2021). "States of insulin resistance including PCOS are found to be associated with lower SHBG levels." (PMID 34063169, 2021).
Insulin resistance (continued). "Although obesity and insulin resistance are associated with an increased incidence of cardiovascular disease, whether they lead to abnormal expression of circulating SHBG or its interaction with androgen signaling remains to be elucidated." (PMID 34335746, 2021). "Additionally, the insulin-resistant state is associated with low SHBG expression, while higher levels of SHBG are associated with lower risk of diabetes development." (PMID 33808055, 2021). "Research directed to elucidate whether plasmatic and cardiac SHBG expression is associated with physiological testosterone levels could represent novel research approaches to study insulin resistance, obesity, diabetes, and heart failure." (PMID 34335746, 2021). "Studies have shown that obesity, insulin resistance, metabolic syndrome and dyslipidemia have a strong association with low serum levels of total testosterone, free testosterone and sex hormone binding globulin (SHBG)." (PMID 33047895, 2020). "In addition, SHBG level is negatively associated with hepatic lipid content and insulin resistance as well as pro-inflammatory markers." (PMID 33291623, 2020). "In addition, a prospective analysis of 1377 young adults reported that SHBG level was associated with future insulin resistance." (PMID 33291623, 2020). "Furthermore, therapies which reverse insulin resistance, for example, metformin, are associated with an increase in SHBG concentrations in women with PCOS." (PMID 33139661, 2020). "Thus, adipose tissue insulin resistance associated with cellular inflammatory factors negatively affect hepatic production of SHBG and accelerate metabolic and reproductive disorders, such as NAFLD/NASH, PCOS and type 2 diabetes." (PMID 33139661, 2020). "Finally, in our study, we found that the factor associated with discrepant IA values were SHBG concentrations and insulin resistance." (PMID 33352636, 2020). "Low serum SHBG levels are associated with insulin resistance and hyperinsulinemia, suggesting that SHBG could be a new risk factor and predictor for the incidence of type 2 DM." (PMID 30057912, 2018). "Numerous publications have proposed that low levels of SHBG are strongly associated with the features of metabolic syndrome and may play an important role in modifying the risk of insulin resistance and its outcomes." (PMID 30455723, 2018). "However, SHBG and calculated free testosterone were associated with both ovarian ultrasound and metabolic parameters, such as BMI and insulin resistance." (PMID 30275830, 2018). "Our hypothesis was that greater socioeconomic disadvantage relates to higher BMI and so would be associated with lower SHBG as a marker of insulin resistance in women." (PMID 28458728, 2017). "Both, SHBG and cognitive status are additionally associated with insulin resistance." (PMID 28498873, 2017). "This strong association has prompted suggestions that a low level of SHBG could be used as a marker to identify individuals with insulin resistance." (PMID 28458728, 2017). "Given the association between lower SHBG and insulin resistance in both men and women and the relation between low SHBG and higher plasma glucose, our findings are further evidence for the link between socioeconomic disadvantage and future risk of impaired glucose regulation." (PMID 28458728, 2017). "Furthermore, one study has indicated that SHBG had a significant inverse association with insulin resistance only in postmenopausal women." (PMID 28587233, 2017). "Moreover, SHBG was proved to have an inverse relation with obesity and insulin resistance and low SHBG levels are an independent risk factor for type 2 diabetes development." (PMID 25790331, 2015). "Moreover, SHBG levels are known to be inversely associated with insulin resistance and are thought to predict the risk on T2DM." (PMID 25415563, 2014). "Low plasma SHBG levels are associated with insulin resistance and other components of MS." (PMID 25653879, 2014).
Insulin resistance (continued). "Even a modest weight loss in overweight or obese women with PCOS reduces insulin resistance, hyperinsulinemia, and hyperandrogenism and increases sex-hormone binding globulin production, thereby improving hirsutism, menstrual cyclicity, ovulation rates, and fertility." (PMID 25221543, 2014). "Obesity-related insulin resistance and resulting hyperinsulinemia may cause a decreased sex-hormone binding globulin production and an increased ovarian androgen production, both of which contribute to the hyperandrogenism." (PMID 25221543, 2014). "Patients with INSR mutation differ biochemically from patients with more common insulin resistance associated with the metabolic syndrome by having high levels of adiponectin, sex-hormone-binding globulin (SHBG), and insulin-like growth factor-binding protein 1 (IGFBP1)." (PMID 23766565, 2013). "First, insulin-resistance and its consequences such as higher insulin-like growth factor (IGFs) bioactivity or lower sex-hormone binding globulin (SHBG) concentration have been associated with increased breast cancer risk in experimental and epidemiological studies." (PMID 24244548, 2013). "We examined the associations of estradiol, testosterone and SHBG with insulin resistance in pre- and in postmenopausal women and postmenopausal women who had received hormone therapy to clarify whether the associations differ depending on the estrogen status." (PMID 23825975, 2013). "Low SHBG has been independently associated with insulin resistance, and it has been suggested that SHBG might have a direct causing role of insulin resistance." (PMID 22518131, 2012). "Hyperinsulinemia or insulin resistance typically associated with diabetes might have resulted in decreased testosterone and SHBG levels (i.e., reverse causality)." (PMID 23066943, 2012). "In addition, decreased levels of plasma SHBG have also been implicated in both insulin resistance and metabolic syndrome." (PMID 20404913, 2010). "Thus, a lower SHBG level, subsequent to insulin resistance, could also contribute to HA and is associated with increased adverse metabolic profiles and hypertension." (PMID 38256617, 2024). "Moreover, several single-nucleotide polymorphisms in the SHBG gene, which might subsequently lead to alterations in serum SHBG levels, were shown to be related to higher risks of insulin resistance." (PMID 39195702, 2024). "However, in recent years, in-depth research on SHBG has generated new insights, suggesting that it is closely associated with metabolic-related phenotypes and diseases such as blood lipids, hepatic fat content, obesity, insulin resistance, and diabetes." (PMID 38796576, 2024). "However, due to inhibition of its synthesis, SHBG can be normal in patients with mixed GH/TSH-secreting pituitary tumors or TSHoma with coincident insulin resistance or in microadenoma cases; conversely, other factors (oral estrogen therapy, anorexia) can cause elevated SHBG in RTHβ." (PMID 37988295, 2024). "Thus, SHBG may be a useful marker of the severity of hepatic insulin resistance and fatty liver that is linked to hepatic insulin resistance." (PMID 36968815, 2023). "In addition, low SHBG is also closely associated with insulin resistance." (PMID 36767197, 2023). "On the other hand, excess weight, insulin resistance, and hyperinsulinemia have been associated with changes in total and bioavailable plasma sex steroid levels in women through a number of mechanisms that can lead to a decrease in plasma SHBG levels, and a rise in bioavailable testosterone." (PMID 35105367, 2022). "In addition, low SHBG levels have been linked with increased insulin resistance, although the exact mechanism connecting insulin resistance and SHBG suppression remains unclear." (PMID 36421197, 2022).